IDH1 (isocitrate dehydrogenase (NADP(+)) 1)
Diseases named in the same sentence as IDH1 in open-access papers (continued):
Sharing a sentence is not in itself a finding about the gene and the disease.
glioma (continued). "Importantly, we observed that TERT promoter mutations particularly C228T and long telomere length significantly impacted radiotherapy outcome in glioma patients, which appears independent of WHO grade, KPS score, IDH1 mutations and MGMT methylation." (PMID 26556853, 2016). "This may hint at a link between CIMP CRC tumors, which are typically associated with BRAF and KRAS mutations but not IDH1 or TET mutations, and CIMP gliomas, which are associated with IDH1 mutations but not BRAF or KRAS mutations." (PMID 27879658, 2016). "IDH1 mutation and co-deletion of chromosome 1p19q, but not the alterations in RTK pathway genes, are the predominant form of somatic genomic alterations in PM gliomas." (PMID 27385209, 2016). "The data further suggested that not all IDH1/2 wild-type lower grade gliomas are uniformly aggressive and additional markers including TERTp mutation and EGFR amplification should be examined in the clinical management of lower-grade gliomas with wild-type IDH1/2." (PMID 26369702, 2015). "However, the p-value between the frequency of different types of gliomas ad the IDH1 positivity failed to reach a statistical significance value (p-value = 0.056)." (PMID 27275230, 2015). "Although patients with IDH1 mutations are generally younger, a multivariate analysis has confirmed that IDH1 mutation can be considered a favorable independent prognostic marker in Grade III and IV gliomas, but not in WHO Grade II astrocytomas." (PMID 24716189, 2014). "Furthermore our OncoPanel analysis revealed that 15% of IDH1/2 mutant gliomas would not be detected by traditional IDH1 (p.R132H) antibody testing, supporting the use of genomic technologies in providing clinically relevant data." (PMID 25257301, 2014). "However, in a direct comparison of 5hmC levels in DNA between IDH1 mutant and IDH1 wild-type gliomas, we did not observe any substantial differences between these two categories of brain tumors." (PMID 23634848, 2013). "We therefore analysed IDH1 and IDH2 statusat codon 132 of IDH1 and codon 172 of IDH2 by direct sequencing and anti-IDH1-R132H immunohistochemistry in 53 paired samples and their recurrences, including 29 low- grade gliomas, 16 anaplastic gliomas and 8 Glioblastomas." (PMID 23840696, 2013). "Here, we tested this hypothesis by treating patient derived IDH1 mutant glioma initiating cells (GIC) with non-cytotoxic, epigenetically targeted doses of the DNMT inhibitor decitabine." (PMID 24077826, 2013). "Blockade of a mutant IDH1 impaired the growth of IDH1-mutant, but not IDH1-wild-type, glioma cells." (PMID 24202337, 2013). "Also of interest, is that a number of common mutations found in some classes of human glial tumors are absent in our PXA cohort, including mutations in IDH1 and IDH2 and that BRAF is not duplicated in PXA." (PMID 21479234, 2011). "A similar effect was also seen for IDH1/2-mutant astrocytoma (non-TCGA cohort status HR: 0.55, P < .01) and IDH1/2-mutant oligodendroglioma (non-TCGA cohort status HR: 0.17, P < .001) even after controlling for features identified above within each glioma subtype." (PMID 39164213, 2025). "Interestingly, our own assessment of the Brain Lower Grade Glioma TCGA PanCancer Atlas dataset highlighted that low expression of TP53I3 and high expression of IL6 and MYC was associated with worse survival in mutant IDH1 tumors but not WT IDH1." (PMID 40188944, 2025). "However, for patients younger than 55 years, or those with a history of lower-grade glioma and/or tumors showing immunohistochemical loss of nuclear ATRX expression, negative IDH1 p.R132H immunostaining should be followed by DNA sequencing to identify less common IDH1 or IDH2 mutations." (PMID 40141375, 2025).
glioma (continued). "Indeed, total IDH1 (IDH1wt and IDH1R132H) protein levels were higher in mIDH cell lines when compared to wtIDH cells and IDH1 and IDH2 expression was highest in PDGFRA+ tumor cells, which are the majority of glioma cells in mIDH tumors and a small percentage of GSCs in wtIDH tumors." (PMID 40060572, 2025). "However, mutations in TCA cycle enzymes, such as isocitrate dehydrogenase (IDH1/2), SDH, or fumarate hydratase (FH), generate oncometabolites like D-2-hydroxyglutarate (D-2HG), succinate, and fumarate, which disrupt epigenetic regulation and promote tumorigenesis in gliomas, AML, and renal cancers." (PMID 40734168, 2025). "However, KAT5 expression on its own failed to predict survival in IDH1/2 mutant or wt gliomas." (PMID 40346033, 2025). "However, the upregulation of some of the lipogenic enzymes after HDAC knockdown potentially suggests a mechanism by which tumor cells might compensate and why some HDAC knockdowns inhibit the growth of IDH1 MT glioma cells and others do not." (PMID 39149696, 2024). "However, our study was neither designed nor powered to find regional signatures within the iTME depending on IDH1 status, but rather to identify common transcriptional differences within the iTME between tumor center, periphery and PBMC of IDH1wt and IDH1mut grade 4 glioma." (PMID 38127790, 2023). "Finally, co-staining with LFB (for myelin structure) and anti-IDH1 R132H antibody in 11 PM gliomas with 1p19q co-deletion and 9 PM gliomas without 1p19q co-deletion confirmed the absence of myelin fibers in tumor regions strongly stained with anti-IDH1 R132H antibody H09." (PMID 37055795, 2023). "However, more recently, results from a phase I/II clinical trial reported that none of the IDH-mutant glioma patients treated with azacytidine in combination with mutant IDH1 inhibitor, olutasidenib, had a clinical response to treatment and all patients progressed within 10 weeks (NCT03684811)." (PMID 37857607, 2023). "In order to exploit radiomic differences between male and female glioma patients that may influence ML prediction model performances, this study aimed to analyze the distribution of radiomics features in between IDH1+/- female and male cases without building or promoting any ML prediction model." (PMID 36816966, 2023). "In this study, we examined the use of whole-genome DNA methylation array (WGMA) testing to identify IDH1/IDH2 pathway disruption, through the detection of CIMP, in addition to the characterization of additional molecular alterations that may assist in the classification of glioma tumors." (PMID 36360312, 2022). "Despite IDH1 is a powerful prognostic marker to distinguish lower grade gliomas and secondary glioblastoma from primary glioblastoma, its potential role as a therapeutic target for gliomas has not yet been determined and further understanding of IDH1 in tumor metabolism is essential." (PMID 33493139, 2021). "Notably, within gliomas, we can divide these molecular biomarkers into those with a point mutation in the IDH1 or IDH2 gene (IDH-mutant), which occurs predominantly in lower-grade gliomas (WHO grade II/III), or else into secondary GBM with no mutation (IDH-wildtype)." (PMID 32977537, 2020). "IDH1 mutations were associated with increased overall survival of GBM patients and occurred preferentially in young patients and those with secondary GBM, that is GBM progressing from a lower grade glioma as opposed to GBMs that arise de novo, i.e., primary GBM." (PMID 31091655, 2019).
glioma (continued). "Similarly, in TCGA cohorts with IDH1 wild-type GBM without glioma CpG island methylation phenotype (G-CIMP), the increased mRNA levels of H2AFJ was significantly (p = 0.034) correlated with a shorter time to new tumor event after patients receiving TMZ, not radiation, therapy." (PMID 31906036, 2019). "However, 2-HG depletion did not inhibit the growth of mutant-IDH1 gliomas." (PMID 30279357, 2018). "The aim of this study was to analyze whether genetic changes of MGMT, IDH1/2 and BRAF occur in PXA or gcGBM and if these genetic changes, respectively their distinct distribution pattern, could be used as molecular markers in the differentiation of these glial tumor entities." (PMID 27253461, 2016). "While this decrease in D-2HG supported that the mutant IDH1 enzyme was being inhibited with AGI-5198 treatment in our chondrosarcoma cell lines, the next question was if we could demonstrate corresponding anti-tumor activity with the compound, similarly to the results seen in gliomas." (PMID 26368816, 2015). "For example, in a diffuse glioma without morphological evidence of oligodendroglioma, IDH1 and ATRX analysis may be carried out initially, but would 1p/19q analysis still need to be performed in gliomas with ATRX mutation or loss of protein expression (ie, molecular evidence of astrocytoma)?" (PMID 24990071, 2014). "In addition, although the IDH1 gene has been discovered as a predictor of glioma survival in previous studies, it could not distinguish GBM patients in our Chinese populations, suggesting the underlying genetic heterogeneity among different populations." (PMID 24194606, 2013). "The recently regulatory-approved vorasidenib, a brain-penetrating oral inhibitor of IDH1/2, has altered the treatment paradigm for recurrent/residual non-enhancing surgically resected CNS WHO grade 2 mIDH gliomas." (PMID 39857783, 2025). "Although the 2021 WHO-CNS21 classification no longer categorizes IDH-mutant gliomas as GBM, we have chosen to retain IDH1-mutant gliomas in our analysis to ensure consistency across datasets and alignment with historical GBM molecular classifications." (PMID 40234567, 2025). "Further, amongst IDH1/2-wild-type tumors, where MGMT-methylation status is instrumental for therapeutic selection, almost a fifth of high-grade gliomas and more than 3-quarters of low-grade gliomas were not assessed for MGMT status." (PMID 39164213, 2025). "A phase III clinical trial of an IDH1 and IDH2 inhibitor vorasidenib yielded promising results among patients with low-grade IDH-mutant gliomas who had undergone initial surgery and no radiation or chemotherapy." (PMID 38931350, 2024). "Morphology along with immunohistochemistry with IDH1 and ATRX can classify gliomas into subtypes without the need for expensive molecular testing in most cases." (PMID 39192927, 2024). "Results showed that IDH1 wild-type gliomas without TMZ had the highest ITGB4 expression, while IDH1-mutant gliomas with TMZ had the lowest." (PMID 38982076, 2024). "The IDH1/2 wild-type (3.5%) but none of IDH1/2-mutant grade II and III gliomas harbored FGFR3-TACC3 fusions." (PMID 39087020, 2024). "The expression levels of EMP3 and CHI3L1 in wild-type IDH-1, non-1P19Q co-deletion, and MGMT non-methylated gliomas were higher than in others." (PMID 37887529, 2023). "Targeted inhibition of the mutant IDH1, but not the wild type IDH1, through AGI-5198 treatment has been found to arrest the growth of gliomas." (PMID 36672415, 2023). "However, it is not known whether Ki-67 expression along with IDH1 can differentiate glioma-grading." (PMID 36147928, 2022).
glioma (continued). "While LITT has been shown to be an effective, well-tolerated alternative to open surgical resection in both low- and high-grade gliomas, LITT treatment outcomes specific to IDH1/2 mutant grade 2 and 3 gliomas have not been studied." (PMID 35448183, 2022). "While PRRS increased as the stage advanced, higher PRRS was also observed in IDH1 wildtype, 1p/19q non-codeleted, and MGMT-promoter unmethylated gliomas compared to their counterparts." (PMID 35990696, 2022). "One hundred and seventy-seven patients with grade IV glioma, 6 with grade III glioma with nonmutated IDH1 and 15 radiologically diagnosed patients were included." (PMID 35371528, 2022). "Interestingly, IDH-1 could not be identified in any of the high-grade tumor specimens, which is congruent with the current literature, suggesting that glioblastoma of the spinal cord may correspond only to primary high-grade glioma." (PMID 33094355, 2021). "Our study included a non-tumoral human cortex sample as a control, five diffuse IDH1-mutant grade II and III gliomas and five GBMs." (PMID 34771555, 2021). "In this study, we found that the mutant genes in the metastatic brain tumors included ALK, MDM2, ATM, BRCA1, FGFR1, and KRAS, and there were no glioma-related mutant genes (MGMT, IDH1, IDH2, 1p/19q, BRAF, and TERT)." (PMID 32973641, 2020). "The mean T/N ratio of FLT-PET/CT in IDH1-wildtype tumours was significantly higher than that in IDH1-mutant tumours among grade II and III gliomas (P = 0.005), but this was not the case for MET-PET/CT." (PMID 32382870, 2020). "The histopathological diagnosis was a glioma, not otherwise specified (NOS) without WHO grading which was IDH1 (R132H) antibody-negative, 1p/19q non-codeleted, and ATRX retained." (PMID 31806041, 2019). "The histopathology of the tumor resected in the second surgery showed a glioma, NOS that was not 1p/19q co-deleted by FISH testing and IDH1 (R132H) was negative by IHC." (PMID 31806041, 2019). "Our finding that only IDH1+ GBMs have expression profiles resembling LGG may indicate that IDH1 mutated GBMs are either misidentified LGGs or represent a unique, LGG-like pathology among high-grade gliomas, this observation does not account the majority of LTS cases." (PMID 27124395, 2016). "Anaplastic astrocytoma (grade III) IDH1 mutant samples were significantly higher for HK2 expression and HK2 activity when compared to normal controls and grade II gliomas (*p < 0.05), but not significantly (ns) different from GBM and GBM cultures." (PMID 27588472, 2016). "Immunostaining with specific antibodies confirmed the expression of IDH1-R132H in gliomas originating from mIDH1-GL261, but not in pGL261 gliomas." (PMID 25849072, 2015). "However, IDH1/2 mutations are not exclusively found in oligodendroglial and oligoastrocytic gliomas, but also in the majority of grade II and III astrocytic tumors, indicating the existence of a common initiating event among these histologically and clinically diverse glioma subtypes." (PMID 24086756, 2013). "In this study, we have demonstrated that promoter hypermethylation of IDH1 and IDH2 genes is absent or very rare in human gliomas and other brain tumors." (PMID 23267435, 2012). "The tumor (negative for IDH1 (R132H) staining, lacking 1p/19q codeletion, with preserved ATRX) exhibited moderate atypia and focal microvascular proliferation, suggestive of a high-grade glioma." (PMID 41596318, 2026). "Notably, a significant proportion of gliomas were not assessed for MGMT-methylation status, especially amongst IDH1/2-mutant tumors." (PMID 39164213, 2025). "The lack of functional IDH1 gene in primary human astrocytes promoted extensive DNA hypermethylation and reshaped the methylome that mimicked the changes noted in G-CIMP-positive lower-grade gliomas." (PMID 37169948, 2023).
glioma (continued). "Finally, we found that the histopathological patterns of recurrent gliomas were related to survival time after reoperation, but the patient age, primary WHO grade, and IDH1 status were not significantly related to the survival time after reoperation." (PMID 36597096, 2023). "Additionally, ARL score was significantly higher in IDH1 wildtype, 1p19q non-codeleted, and MGMT unmethylated gliomas (p < 0.05)." (PMID 34211979, 2021). "Lastly, other nontargeted strategies for IDH1 mutant AML may include PARP inhibitors such as olaparib and talazoparib, already tested in IDH positive gliomas and in studies using AML cellular models." (PMID 32033196, 2020). "However, recent human clinical data in IDH1 and IDH2 mutant AML, where not all mutant patients respond to inhibitor treatment, points to the plausibility that not all mutant glioma patients will respond to such therapy." (PMID 29062039, 2017). "As a first approach, we used conventional PCR to amplify IDH1 gDNA sequences, however, IDH1G395A was observed in none of the low-grade gliomas, and only in 4 of the high-grade glioma samples, including HGUGM008, for which the presence of IDH1R132H was detected on a surgical solid sample by IHC." (PMID 27902458, 2017). "The mouse conditional knock-in models with mutant IDH1 induced in Nestin-expressing cells were reported to die directly after birth, while the analogous GFAP-induced models survived slightly longer, but did not develop gliomas during their lifespan." (PMID 27145078, 2016). "In addition, according to WHO CNS5, patients older than 55 years without immunoreactivity to IDH1 R132H, with the histopathological characteristics of GBM, with other than midline location, and with no history of glioma, will be diagnosed as GBM IDH-wild-type CNS WHO grade 4." (PMID 39057054, 2024). "Previous work has also considered how molecular markers may be used in clinical decision-making for recurrent surgery for high-grade gliomas particularly for unmethylated MGMT promoter and wildtype IDH1 gliomas—since no other treatment option has demonstrated a survival benefit for these subgroups." (PMID 39767640, 2024). "However, our results show that glutamine, glutamate and GABA energy substrates could significantly increase oxygen consumption rate in IDH1 wild-type U251 glioma cells (approximately 20% increase in OCR), but not in their IDH1-mutant counterpart cells." (PMID 30404651, 2018).